DNMT1 (DNA methyltransferase 1)
Diseases named in the same sentence as DNMT1 in open-access papers (continued):
Sharing a sentence is not in itself a finding about the gene and the disease.
colon carcinoma (continued). "Furthermore, the expression levels of DNMT1 and CDKN2A were measured in colon cancer cells following treatment with the DNMT1 inhibitor, 5-azacytidine, and DNMT1 overexpression plasmid." (PMID 33959155, 2021). "Peroxisome proliferator activated receptor alpha (PPARα), a nuclear receptor that regulates lipid homeostasis, inhibits DNA methyltransferase 1 (DNMT1)-mediated cyclin dependent kinase inhibitor 1A (CDKN1A) and PRMT6-mediated cyclin dependent kinase inhibitor 1b (CDKN1B) to promote colon cancer." (PMID 35004688, 2021). "Heterogeneous degrees of DNMT1 overexpression are associated with primary colon cancer cells, while DNMT3B overexpression has been related to CIMP-high colon cancer, although the overexpression of the protein not always parallels the RNA levels." (PMID 32806509, 2020). "Moreover, it has been established that DNA methyltransferase 1 (DNMT1), which is responsible for DNA methylation, is also a downstream factor regulated by HSP90 in human pancreatic and colon cancers." (PMID 30925862, 2019). "We took advantage of the development of an isogenic cell line obtained from the human colon cancer cell line HCT-116, where the DNA methyltransferases 1 (DNMT1) and 3B (DNMT3B) genes have been genetically disrupted by homologous recombination (double knockout cells, DKO)." (PMID 30018746, 2018). "By endogenous co-immunoprecipitation, we found KDM1A to bind DNMT1 and DNMT3B in two different cancer cell lines: when we immunoprecipitated endogenous KDM1A from whole-cell extracts of the colon cancer cell line HCT116, we detected DNMT1 and DNMT3B by western blotting." (PMID 27449289, 2016). "Intriguingly, overexpression of DACOR1 in colon cancer cells resulted in a gain of DNA methylation at multiple loci without changing the DNMT1 expression level." (PMID 27408682, 2016). "For instance, the knockout of DNMT1 or DNMT3B alone in the human colon cancer cell line HCT116 does not impact DNA methylation, while their concomitant invalidation induces profound hypomethylation leading to a minimal methylation footprint on DNA." (PMID 25948775, 2015). "To investigate whether inhibition of DNA methylation with the DNMT1 inhibitor DAC would increase CaSR expression, we initially treated all five colon tumor cell lines: Coga1A, Coga13, Caco2/AQ, HT29, and LT97 with 1 μM DAC for 72 hr (data not shown)." (PMID 24691920, 2014). "Recent studies suggest that an interaction between DNMT1 and DNMT3B may be vital for the maintenance of patterns of DNA methylation in human colon-cancer cells, particularly in repeat regions and imprinted genes." (PMID 24822169, 2014). "DNMT1 and DNMT3B modulate distinct polycomb-mediated histone modifications in colon cancer." (PMID 24822169, 2014). "Furthermore, overexpression of DACOR1 in colon cancer cells resulted in a gain in DNA methylation at multiple loci without changing the DNMT1 expression level." (PMID 35054945, 2022). "Finally, the up-regulation of Cip/Kip genes and down-regulation of DNMT1 gene is not the only molecular pathways of apoptosis in colon cancer." (PMID 34466608, 2020). "Additionally, drug-induced demethylation was compared to methylation patterns of isogenic colon cancer cells lacking both DNA methyltransferase 1 (DNMT1) and DNMT3B." (PMID 21408221, 2011). "However, in primary colon cancer, methylated BNIP3 does not exhibit high expression but rather shows a downregulated trend, and this downregulation is associated with abnormal methylation mediated by DNA methyltransferase 3β (DNMT3β) and DNA methyltransferase 1 (DNMT1)." (PMID 39763653, 2024). "Here, we mapped and compared the site-specific N-glycoproteomes of colon cancer HCT116 cells and isogenic non-tumorigenic DNMT1/3b double knockout (DKO1) cells using Fbs1-GYR N-glycopeptide enrichment technology and trapped ion mobility spectrometry." (PMID 36639722, 2023).
colon carcinoma (continued). "It should be noted however that PC3 cells contain moderate levels of DNMT1 and DNMT3a which are not affected when DNMT3b is silenced (data not shown); like PC3, colon cancer cells also express DNMT1 and DNMT3a." (PMID 18798999, 2008). "Additionally, the expression of ARID1B was positively correlated with the expression of three methyl transferases (DNMT1, DNMT3A, and DNMT3L) in colon cancer, although the difference was not significant." (PMID 36313455, 2022). "We compared HCT116 colon cancer cells and HCT116 double knock out (DKO) cells that have been genetically disrupted to give severe haplo-insufficiency of DNMT1, and complete absence of DNMT3B, enzymes for DNA methylation maintenance and de novo DNA methylation, respectively." (PMID 24162015, 2013).
acute myeloid leukemia (127 papers, 2006 to 2025). Acute myeloid leukemia (AML) is a group of neoplasms arising from precursor cells committed to the myeloid cell-line differentiation. "Mutations, or increased expressions of DNMT1, 3A, or 3B, are found in numerous cancers (colorectal, pancreas, liver, bladder, breast, acute myeloid leukaemia) (reviewed in Timp and Feinberg)." (PMID 28587163, 2017). "DNMT1 has been proved to be a key regulator in MYCN expression in patients with acute myeloid leukemia." (PMID 41142119, 2025). "The DNMT1 inhibitor 5-aza-cytidine is successfully used in the clinic against Myelodysplasia and Acute Myeloid Leukemia but has limitations such as high toxicity, rapid degradation, and emergence of resistance." (PMID 38580649, 2024). "Recently, a reversible DNMT1-selective inhibitor has been developed with improved tolerability and efficacy in acute myeloid leukemia." (PMID 36755342, 2023). "Ectopic overexpression of miR-148a decreased DNMT1 expression in acute myeloid leukemia, gastric cancer, hepatocellular carcinoma, pancreatic cancer, and prostate cancer cells." (PMID 36959680, 2023). "Together with other DNMTs, DNMT1 was substantially overexpressed in leukemia cells specifically according to leukemia type; likewise, acute myeloid leukemia (AML) cells with methylated p15(INAK4B) expressed higher levels of DNMT1 and DNMT3B." (PMID 36614080, 2022). "For example, findings from acute myeloid leukemia cells have indicated strong impact of miR-29 family members on three target DNMT izoenzymes: DNMT1, DNMT3A and DNMT3B resulting in global DNA hypomethylation as well as reexpression of tumor suppressor genes." (PMID 33803981, 2021). "Treatment of ML-1, Kasumi-1 and MV4-11 acute myeloid leukemia cells with TQ induced a significant decrease in the expression of DNMT1 and DNMT3A proteins." (PMID 33922029, 2021). "DNMT1 and DNMT3b are found to plays roles in the development of central nervous system, while DNMT3a has important functions in acute myeloid leukemia." (PMID 32408199, 2020). "The natural compound harmine inhibited DNMT1 in acute myeloid leukemia cell lines through decreased DNMT1 gene expression, thus promoting p15 promoter demethylation." (PMID 32365701, 2020). "SP1 modulated the expression of DNMT1 gene through mechanisms such as protein abundance, post‐translational modifications or interaction with other transcription factors in human acute myeloid leukaemia cells." (PMID 28840963, 2018). "A previous study has also reported that miR-29b promotes global DNA hypermethylation by targeting directly DNMT3A and 3B and indirectly DNMT1 in acute myeloid leukemia." (PMID 28886082, 2017). "Aberrant DNA methylation is a hallmark of acute myeloid leukemia (AML); however, the regulation of DNA methyltransferase 1 (DNMT1), which is responsible for maintenance of DNA methylation patterns, has largely remained elusive." (PMID 27259275, 2016). "The miR-126/DNMT1 axis is involved in azacitidine resistance in acute myeloid leukemia." (PMID 39796183, 2025). "Similarly, the catalytic activity of DNMT1 can be blocked by azacitidine or decitabine, both used to treat acute myeloid leukemia." (PMID 40901948, 2025). "We thus aimed to investigate whether targeting the epigenetic regulator DNMT1 using 5-azacytidine (5-AzaC), a hypomethylating agent in clinical use for the treatment of acute myeloid leukemia and myelodysplastic syndromes, is efficacious in SHH-MB as well." (PMID 39107797, 2024). "The second was a confirmation of the functional connection between the inhibition of the NF-κB pathway and epigenetic modulation induced by curcumin, through downregulation of DNA methyltransferase 1, which was discovered in a mouse model of acute myeloid leukemia." (PMID 37376060, 2023). "DNMT1 alterations have been described in colorectal cancer, whereas DNMT3A mutations have been often reported in myelodysplastic syndromes (MDS) and are associated with poor survival in acute myeloid leukemia (AML)." (PMID 33339101, 2020).
acute myeloid leukemia (continued). "Similarly in acute myelogenous leukemias, DNMT1, DNMT3a, and DNMT3b levels were significantly upregulated when compared to control bone marrow cells." (PMID 24822169, 2014). "Inhibition of these proteins resulted in the downregulation of DNMT1 and a decreased clonogenic potential of cancers cells in acute myeloid leukemia (AML) and chronic myeloid leukemia (CML)." (PMID 36059621, 2022). "Obesity-induced pro-inflammatory cytokines promote the expression and enzymatic activity of DNMT1 in adipose tissue and acute myeloid leukemia (AML) cells." (PMID 34183666, 2021). "In the acute myeloid leukemia (AML), curcumin downregulated the expression of DNMT1 in diverse cell lines in vivo and in ex vivo models." (PMID 30881375, 2019). "At the moment, the only two DNMT1 inhibitors approved by the FDA are azacitidine and decitabine for the treatment of acute myeloid leukemia and myelodysplastic syndrome." (PMID 39595939, 2024). "In vivo and ex vivo models of acute myeloid leukemia (AML), curcumin downregulated the expression of DNMT1." (PMID 36233012, 2022). "Curcumin inhibits DNA methylation by covalently blocking the catalytic thiolate of DNMT1 and reducing the expression of tumor suppressor gene Sp1 Transcription Factor (Sp1) and Transcription factor p65 (p65) in acute myeloid leukemia (AML) cell lines in vitro and in vivo." (PMID 35774614, 2022). "Overexpression or enhanced catalytic activity of DNMT1, DNMT3a, and DNMT3b has been observed in multiple cancers, including acute myeloid leukemia (AML), chronic myeloid leukemia (CML), glioma, and breast, gastric, colorectal, hepatocellular, pancreatic, prostate, and lung cancers." (PMID 33572577, 2021). "AGT was negatively related to DNMT3A/DNMT3B in acute myeloid leukemia (LAML) and to DNMT1/DNMT3B in LGG." (PMID 34671200, 2021). "Our work is supported by previous observations with detacibine (5-aza-2′-deoxycytidine), another DNMT1 inhibitor, which has shown a similar apoptosis-inducing ability via the TRAIL pathway in acute myeloid leukemia and in HRASG12V-transformed cells." (PMID 34439091, 2021). "In addition, FABP4 promoted aggressive acute myeloid leukemia (AML) in obesity by enhancing aberrant DNA methyltransferase 1 (DNMT1)-dependent DNA methylation of tumor cells." (PMID 33339340, 2020). "In acute myeloid leukemia cells, miRNA-29b inhibited the expression of SP1 (specific protein-1, TF required for DNMT1 expression) and consequently decreased DNMT1 expression." (PMID 29449903, 2018). "Also, gold nanoparticles targeted the epigenetic pathway for acute myeloid leukemia therapy, by targeting the NCL/miR-221/NFkB/DNMT1 signaling pathway." (PMID 34944582, 2021). "DNMT1, DNMT3A, and DNMT3B are overexpressed across several types of cancer lineages, including acute myeloid leukemia (AML), melanoma, breast cancer, colorectal cancer, prostate cancer, and stomach cancer." (PMID 36329185, 2022). "Overexpression of DNMT1 led to PTEN downregulation due to the CpG island methylation in promoter, which promoted tumorigenesis of breast cancer, ovarian cancer and acute myeloid leukemia (AML)." (PMID 30217221, 2018).
colorectal cancer (125 papers, 2007 to 2026). A primary or metastatic malignant neoplasm that affects the colon or rectum. "DNMT1-induced NR3C1 hypermethylation is associated with colorectal cancer cells, and NR3C1 restoration inhibits pro-angiogenic effects on the cells." (PMID 40995432, 2025). "DNMT1 ablation in human colorectal carcinoma cells results in mitotic catastrophe and loss of cell viability, whereas HAP1 DNMT1 KO cells show increased DNA damage response and apoptosis but are viable." (PMID 40112032, 2025). "Loss of DNMT1 protein in the human colorectal carcinoma cells results in chromosomal defects and apoptosis." (PMID 40112032, 2025). "We generate and validate degron alleles of UHRF1 and/or DNMT1 in human colorectal cancer cell lines." (PMID 38580649, 2024). "A parallel study suggested that in KRAS mutant colorectal cancer, DNMT1 is recruited by ZNF304 to cause de novo methylation of several genes including CDKN2A16." (PMID 33514701, 2021). "Since the risk for colorectal cancer increases with aging, an in-depth analysis of the effect of DNMT1 reduction appears to be necessary." (PMID 33401659, 2021). "In colorectal carcinoma, knockout of both DNMT1 and DNMT3B caused promoter demethylation of TIMP3, thus increasing the TIMP3 mRNA level." (PMID 31624299, 2019). "Demethylation to <~30% of wild type levels triggers apoptosis, and deletion of conditional alleles of DNMT1 in human HCT116 colorectal carcinoma cells triggers a mitotic catastrophe and apoptosis." (PMID 25960928, 2014). "For instance, DNMT1 mutations have been described in colorectal cancer, and the disrupted activity of DNMT1 in mice was reported to induce repetitive insertions of a transposable element within the Notch gene leading to its oncogenic activation in thymic lymphomas." (PMID 36979633, 2023). "Mutations in coding regions of the DNMT1 have been reported in colorectal cancer, such as a single base deletion in exon 23 resulting in deletion of the whole catalytic domain; a point mutation in exon 35 resulting in an amino acid substitution in the catalytic domain." (PMID 23049933, 2012). "Here we investigate the role of DNMT1 in shaping the cancer methylome by conducting whole genome bisulfite sequencing (WGBS), repli-seq and ChIP-seq on DNMT1 knockout HCT116 colorectal cancer cells (DNMT1 KO cells)." (PMID 41926459, 2026). "DNMT1, an essential enzyme that maintains DNA methylation, was expressed at a higher level in colorectal cancer than in adjacent normal tissues." (PMID 40125618, 2025). "The DNMTi decitabine, azacitidine and aza-T-dCyd were used in this in vitro and in vivo study, where all three DNMTi inhibited the expression of DNMT1, inhibited cell growth and induced cytotoxicity and/or apoptosis of colorectal cancer cells." (PMID 40011240, 2025). "The present study revealed a crucial epigenetic mechanism in colorectal cancer (CRC) progression involving the aberrant regulation of DACH1 by DNMT1 based on the combination of clinical sample analysis with bioinformatic databases." (PMID 40370966, 2025). "In a follow up study, the authors showed a link between TET2 and resistance to DNMTi in DNMT1 depleted colorectal cancer cells." (PMID 40011240, 2025). "In parallel to our work, a degron approach has been recently applied by other authors to DNMT1 in DLD-1 colorectal cancer cells." (PMID 40595593, 2025). "Of note, PGE2, which is the most abundant prostanoid in colorectal cancer, promotes anti-tumor immune responses by inducing Treg and MDSCs and promotes tumor initiation and growth by upregulating the expression of DNMT1 and DNMT3B." (PMID 38607004, 2024). "To enable the comparative study of DNA methylation maintenance dynamics supported by UHRF1 and DNMT1, we engineered HCT116 human colorectal carcinoma cells to express dox-inducible shRNAs targeting the UHRF1 or DNMT1 3′UTRs." (PMID 39607687, 2024).
colorectal cancer (continued). "In colorectal cancer, miR-515-5p directly inhibits DNMT1, while circ_0040809 competes with miR-515-5p to restore DNMT1 expression." (PMID 37781524, 2023). "DNMT1 phenotype in HCT116 DNMT1+/+ and DNMT1−/− colorectal cancer cells were confirmed by probing with DNMT1 antibody." (PMID 37045940, 2023). "For instance, declined TMSB10 expression was involved in the DNMT1/miR-152-3p/TMSB10 axis to suppress the colorectal cancer development." (PMID 38035023, 2023). "NUSAP1 silencing inhibited DNMT1 expression, leading to the inhibition of liver and colorectal cancer progression." (PMID 35739489, 2022). "RG108 is a DNMTi designed to inhibit the active site of DNMT1 and has low cytotoxicity in colorectal cancer cells and promyelocytic leukemia cells." (PMID 35453513, 2022). "Reduction of Dnmt1 in an ApcMin/+ colorectal cancer mouse model completely suppresses polyp formation and a reduction in hypermethylation." (PMID 36329185, 2022). "MiR-148a expression is decreased in colorectal cancer cells, and this downregulated expression activates DNA-methyltransferase 1 (DNMT1)." (PMID 35743255, 2022). "Milk exosomal miR-148a targets DNMT1 and therefore inhibits the activity of this important activator of colorectal cancer." (PMID 35743255, 2022). "As a first approach to meDNA-guided alternative splicing and its possible impact on cancer, we examined HCT116 human colorectal cancer cells with the DNA methylases DNMT1 and DNMT3b inactivated." (PMID 34086943, 2021). "In colorectal cancer cells, a direct protein-protein interaction between β-catenin, the central effector of canonical Wnt signaling and DNMT1 was identified." (PMID 33401659, 2021). "As we reported in the current article, others have indicated a decreased expression of DNMT1 has been reported following treatment with 5-Aza-CdR in colorectal cancer HCT 116, HT-29, MIP101, and RKO cell lines." (PMID 34466608, 2020). "NUSAP1 gene silencing induced cell apoptosis and inhibited cell proliferation, cell migration, cell invasion, and EMT in colorectal cancer by inhibiting DNMT1 gene expression." (PMID 32153633, 2020). "This study was to investigate that how DNMT1 affected the biological characteristics of colorectal cancer (CRC) cells via modulating methylation of microRNA (miR)‐152‐3p and thymosin β 10 (TMSB10) expression." (PMID 32918845, 2020). "We also showed that expression levels of DNMT1 and TET3 are associated and correlated within the inflamed tunica muscularis of colorectal cancer tissue as well as in the jejunal tunica muscularis of both Dnmt1-WT and Dnmt1-KO mice." (PMID 29700293, 2018). "miR-23b together with a number of miRs were found to be overexpressed in human colorectal carcinoma HCT116 double DNMT1 and DNMT3b knockout (DK) cells as compared to the HCT116 parental cells." (PMID 28077801, 2017). "More recent studies reported the ability of this miRNA to counteract cell proliferation and invasion through inhibition of DNA methyltransferase 1 in SW480 colorectal cancer cells and inhibition of the transcription factor FOXM1 in cervical cancer cells." (PMID 26919240, 2016). "In the HCT116 colorectal cancer cell line, ablation of the catalytically active DNMT1 results in cell cycle arrest and apoptosis due to increased chromosomal instability." (PMID 26808831, 2016). "(2010) both found that stimulation of multiple myeloma or colorectal carcinoma cell lines with the same concentration of rIL‐6 as utilized within the present study (100 ng·mL−1) resulted in significant increases in DNMT1 mRNA." (PMID 26660547, 2015). "In this study, we decided to identify promoter methylation status of ten genes encoding WNT negative regulators, and measure the expression of DNMT1 enzyme in colorectal cancer samples." (PMID 25107489, 2014).